SIRT3 (sirtuin 3)
Diseases named in the same sentence as SIRT3 in open-access papers (continued):
Sharing a sentence is not in itself a finding about the gene and the disease.
breast cancer (continued). "SIRT3, a major mitochondrial NAD+-dependent deacetylase, which has been related to poor prognosis in breast cancer, is a target gene of ERRα/PGC-1α." (PMID 30235254, 2018). "We found that breast cancer cells treated with HNK exhibited an increase in the expression of SIRT1 and SIRT3 within 30 minutes post-treatment." (PMID 26359358, 2015). "We also reported the same inverse correlation between SIRT3 and SOD1 using immunohistochemistry on a tissue microarray of primary breast cancers." (PMID 24955214, 2014). "Similar functional effects of Apigenin were observed by using an additional human breast cancer cell model (MDA-MB-468, TNBC, highly metastatic) whose stemness features were abolished by the inhibition of sirtuin-3 (SIRT3) and sirtuin-6 (SIRT6) protein levels, as supported by in silico analyses." (PMID 38791608, 2024). "KMP inhibits SIRT3 and SIRT6 in TNBC, thereby promoting breast cancer progression." (PMID 39479446, 2024). "Sirtuin 3 (SIRT3), the protein that maintains mitochondrial homeostasis plays an important role in the regulation of autophagy, a process promoted by RSV in 4T1 breast cancer cells by upregulation of the SIRT3/AMPK autophagy pathway." (PMID 39220125, 2024). "Moreover, SIRT3 deacetylates and inactivates Cyclophilin D (CYPD) and inhibits breast cancer glycolysis." (PMID 39479446, 2024). "Moreover, decreased SIRT3 activity and acetylation of SOD2 have been reported in various cancers such as breast cancer and hepatocellular carcinoma." (PMID 37533102, 2023). "Within the same breast or mammary tumors, some cells are positive for SIRT3 and others are negative." (PMID 35571098, 2022). "To test this hypothesis, we used breast cancer cell lines (MCF-7 and MDA-MB-231), and we analyzed the expression of HIF-1α, PDK1, PDH, SIRT1, SIRT3, and ROS for mitochondrial metabolic pathway." (PMID 34771733, 2021). "SIRT3 and SOD2 are decreased in the breast carcinoma cells with activated UPRmt." (PMID 34717757, 2021). "Furthermore, SIRT3 also suppresses HIF1-α and its targeted genes as has been demonstrated in human colon carcinoma, osteosarcoma cells and breast cancer cells." (PMID 29212260, 2017). "In addition to SIRT3, we recently reported that SOD2 itself is down-regulated in breast cancer cell lines upon activation of oncogenes, such as Ras." (PMID 24955214, 2014). "There was no overall difference observed in SIRT3 expression between breast cancer and normal breast tissue." (PMID 17003781, 2006). "The upregulation of SIRT3 due to UPRmt elevates the ROS production and stabilization of HIF-1α, which initiates the switching of the anaerobic glycolytic process, the Warburg effect in various carcinomas, including breast cancer, hepatic, gastric, and colorectal carcinoma." (PMID 34717757, 2021). "Under glucose deprivation, our data showed that the inhibitor or activator of AMPK could not change the cell death rate of the breast cancer cells with SIRT3 knockdown." (PMID 32630312, 2020). "We found that markers of activation of the SIRT3 axis of the UPRmt could distinguish metastatic from non-metastatic cells in a panel of breast cancer cell lines." (PMID 28798902, 2017). "Additionally, in a collection of 50 matched primary and metastatic lesions from breast cancer patients, using SOD2 as a marker, we observed a significant increase in activation of the SIRT3 axis of the UPRmt, in metastatic lesions when compared with primary lesions." (PMID 28798902, 2017). "However, in subgroup analyses, for lymph node metastasis of breast cancer in the SIRT3 positivity/high group, as compared with the SIRT3 negative/low group, was statistically significant (OR = 2.20, 95% CI = 1.49–3.26, P<0.0001)." (PMID 27483432, 2016).
breast cancer (continued). "We have previously demonstrated that MEFs lacking Sirt3 exhibit an immortalization permissive phenotype and the knockout mice spontaneously form well differentiated, estrogen and progesterone (ER/PR)-positive mammary tumors." (PMID 21386137, 2011). "Thus, Sirt3 silencing seems to be beneficial in oral and esophageal carcinomas, where it protects cells from death, while in lung, colon, breast carcinomas the role of Sirt3 is not clear, and its suppression could have protumor effect." (PMID 35938164, 2022). "The significance of Sirt3 in breast cancer cells lies in the fact that only 23% of normal breast tissue shows to be negative for Sirt3 expression, whereas even up to 72% of in situ breast lesions and 74% of invasive lesions are negative for the expression of Sirt3." (PMID 32244715, 2020). "In this regard, the Sirt3 knockout mice do not begin to develop mammary tumors until after 12 months of age the immunohistochemical staining has identified these tumors as well differentiated estrogen (ER) and progesterone (PR) receptor positive mammary tumors." (PMID 22016654, 2011). "Therefore, because the majority of breast cancers are negative for the expression of Sirt3, we conclude that by reverting its expression in MCF-7 cells, breast cancer cell normalization could be induced." (PMID 32244715, 2020).
diabetes (117 papers, 2009 to 2025). "Recent evidence has indicated that SIRT3 deficiency or functional abnormality is closely associated with the initiation and progression of various disorders, such as diabetes, cardiovascular diseases, neurodegenerative diseases and cancer." (PMID 37481555, 2023). "SIRT3 deficiency has been shown to be associated with MetS, the precondition for diabetes, cardiovascular diseases, and obesity, collectively known as comorbidities, which can coexist with AD." (PMID 36675125, 2023). "Collectively, our findings revealed the protective role of SIRT3 against diabetes-associated cognitive decline, making it a novel therapeutic candidate for the treatment of diabetes-related cognitive diseases." (PMID 37481555, 2023). "Electron microscopy studies of the hippocampus CA1 region revealed that SIRT3 reversed diabetes-induced synapse loss." (PMID 37481555, 2023). "SIRT3 deficiency is associated with metabolic syndrome (MetS), a precondition for diseases including obesity, diabetes, and cardiovascular disease." (PMID 36675125, 2023). "Exposure of ECs to HG as in diabetes decreases Sirt3 expression, leading to increased senescence-associated galactosidase and loss of the ability to form tubular networks." (PMID 36675125, 2023). "A growing body of evidence shows that SIRT3 downregulation contributes to aging-associated diseases including diabetes, cardiovascular diseases, and neurodegenerative diseases such as AD, PD, HD, and ALS." (PMID 36675125, 2023). "The anti-inflammatory role of SIRT3 is associated with oxidative stress in diabetes induced kidney injury." (PMID 35956936, 2022). "The results from our data make it clear that ameliorating the level of SIRT3 in the EC can be a future strategy in combating diabetes-associated kidney fibrosis." (PMID 33981977, 2021). "Hyperacetylation of mitochondrial proteins due to SIRT3 deficiency has been shown to associate with cardiovascular, neurodegenerative diseases, diabetes, and aging." (PMID 31614941, 2019). "To probe the reason for robust SIRT3 deficiency in the diabetes-associated fibrosis in kidney, we analyzed peroxisome proliferator-activated receptor-gamma coactivator (PGC)-1α which is known to regulate SIRT335–37." (PMID 30250024, 2018). "In a rodent model of pre-diabetes, oxidative stress induced by a high-fat diet was associated with disruption of the SIRT3/PGC-1α axis with impairment in mitochondrial bioenergetics and decreased testicular mtDNA and adenylate energy charge." (PMID 26370974, 2015). "We identified a SNP in the promoter of Sirt3 that is probably responsible for the lower expression of Sirt3 in the liver of GK rats, and for downstream variation in protein acetylation in enzymes and pathways linked to diabetes and the metabolic syndrome." (PMID 24743600, 2014). "The associations of several SNPs in UCP4, 5, and SIRT3, 5 with plaque number varied by smoking status, diabetes and hypertension." (PMID 22087257, 2011). "Some modifications by hypertension and diabetes were also observed in the association of SIRT3, SIRT5 and UCP5 genetic variants with carotid plaque." (PMID 22087257, 2011). "ROS-related damage has been implicated in cancer, aging, diabetes, and neurodegenerative diseases, and SIRT3 plays important roles in reducing cellular ROS level." (PMID 20661474, 2010). "Additionally, it has been reported that a decrease in Sirt1 and Sirt3 levels in diabetes can cause cardiac complications by acting on mitochondrial proteins." (PMID 38134189, 2023). "Hence, our findings provide a novel pathologic and therapeutic understanding of SIRT3 in diabetes-associated cognitive impairment." (PMID 37481555, 2023). "The loss of SIRT3 can leads to induction of abnormal glycolysis and defective metabolism of kidney tissues, which is responsible for the progression of kidneys fibrosis in diabetes." (PMID 36923354, 2023).
diabetes (continued). "Furthermore, targeting the activation of SIRT3 by honokiol provides a promising therapeutic candidate for diabetes-associated cognitive dysfunction." (PMID 37481555, 2023). "Similarly, SIRT3 improves cardiac dysfunction caused by diabetes by activating FoxO3a-mediated mitochondrial autophagy." (PMID 37196115, 2023). "SIRT3 can prevent or even reverse retina, bone and heart damage caused by diabetes." (PMID 35002528, 2022). "In diabetic kidneys, SIRT3 deficiency increases aberrant glycolysis, which is responsible for the fibrogenic pathway, and inhibiting abnormal glycolysis by SIRT3 restoration can prevent diabetes-related kidney fibrosis." (PMID 35457114, 2022). "SIRT3 deficiency is one of the fibrotic phenotypes in diabetes that leads to PKC activation and PKM2 tetramer-to-dimer interconversion; ultimately, these processes alter the metabolic switch toward defective metabolism and associated mesenchymal activation in renal epithelial cells." (PMID 33981977, 2021). "We hypothesize that modulation of Sirt1 and Sirt3 protein activity independently or in a combination may improve mitochondrial function as well as diabetes-associated cardiac complications." (PMID 33668369, 2021). "It implicated that SIRT3 may serve as a potentially promising therapeutic target for skin wound healing in diabetes." (PMID 32119761, 2020). "Furthermore, reduced SIRT3 expression is associated with cell aging and downregulated in metabolic syndrome, hyperlipidemia, diabetes, and smoking, thus related with human longevity." (PMID 33149809, 2020). "Third, we next intend to use STZ-induced diabetes in Sirt3-deficient mice as a model and investigate whether the protective effects of MSCs on lung injury are Sirt3-dependent." (PMID 32089781, 2020). "In conclusion, SIRT3 deficiency delays skin wound healing in diabetes, the mechanism may be related to impaired mitochondria function, enhanced oxidative stress and increased necroptosis." (PMID 32119761, 2020). "Collectively, SIRT3 deficiency delayed skin wound healing in diabetes, the mechanism might be related to impaired mitochondria function, enhanced oxidative stress and increased necroptosis." (PMID 32119761, 2020). "Next, we verified that the skin wound was further delayed in diabetes if SIRT3 was deficient." (PMID 32119761, 2020). "SIRT3 expression is down-regulated with age, and its deficiency is accompanied with mitochondrial protein hyperacetylation, resulting in aging-associated diabetes, cancer, and inflammation." (PMID 31806859, 2019). "Restoration of SIRT3 could be an alternative strategy in combating diabetes associated-kidney fibrosis via inhibition of aberrant glycolysis." (PMID 30250024, 2018). "Moreover, in humans a SIRT3-polymorphism with loss of function is associated with pulmonary arterial hypertension and propensity to develop diabetes." (PMID 28423723, 2017). "Our data suggest that modification of Sirt3 with APLN could be used as a novel therapy strategy for the treatment of diabetes-associated impairment of angiogenesis after MI." (PMID 25311234, 2015). "Our data suggest that modification of Sirt3 with apelin could be used as a novel therapy strategy for the treatment of diabetes-associated heart failure." (PMID 29167823, 2015). "Given the results concerning SIRT3 negative modulation and considering the critical role of this sirtuin in diabetes-associated oxidative stress and endothelial dysfunction, we explored whether SIRT3 silencing (p < 0.001 vs. NT) could affect the beneficial effects of 3-kDa WH on T2DM-induced stress." (PMID 37372041, 2023). "In this study we found the suppression of SIRT3 protein level in diabetic kidney, displays responsibility in fibrogenic programming associated with aberrant glycolysis and such abnormal glycolysis is the therapeutic target in diabetes associated-kidney fibrosis." (PMID 30250024, 2018). "SIRT3 regulates mitochondrial metabolism, insulin resistance, and insulin signaling in diabetes mellitus." (PMID 41304967, 2025).
diabetes (continued). "Exposure to As through digestion can lead to the development of diabetes via the sirtuin 3 (SIRT3)-forkhead box O3 (FOXO3a) pathway." (PMID 41488239, 2025). "In both the in vitro and in vivo diabetes models, decreased SIRT3 expression was observed, which led to the hyperacetylation of FOXO3 and suppression of the mitophagy pathway." (PMID 41304967, 2025). "SIRT3 also contributes to diabetic osteoporosis, a complication of type 2 diabetes mellitus marked by impaired osteoblast function and disrupted bone microarchitecture." (PMID 41304967, 2025). "In summary, luteolin confers cardioprotection against post-resuscitation injury in diabetes primarily by activating the Sirt3 signaling pathway." (PMID 40635895, 2025). "By regulating each other’s activity, Sirt6 and Sirt3 shield the heart against diabetes-mediated cardiomyopathy brought on by obesity." (PMID 41567643, 2025). "It has been reported that SIRT3 expression is significantly reduced in the kidneys of BTBR ob/ob mice with type 2 diabetes mellitus, which correlates with its reduced activity and elevated ROS levels." (PMID 40227196, 2025). "Although SIRT3 plays an important role in cardiovascular diseases and other diabetes-related complications, few studies have investigated its role in DR." (PMID 39564112, 2024). "Several studies have reported the importance of SIRT3 in cardiovascular diseases and diabetes-related complications." (PMID 39564112, 2024). "The results indicate that dihydromyricetin alleviates endothelial dysfunction in diabetes via the inhibition of OS in a SIRT3-mediated way." (PMID 39064844, 2024). "Specific activation of SIRT3 reduces oxidative stress induced by diabetes, protecting podocytes and glomeruli from damage." (PMID 39431155, 2024). "Experimental results show that regulating the SIRT3 pathway can improve diabetes-induced kidney damage." (PMID 39431155, 2024). "SIRT3 involved in insulin resistance and diabetes mellitus, and has protective effect in retina, skeletal muscle and heart injury by diabetes." (PMID 38698042, 2024). "In the present study, we observed that CD38 was up-regulated in the heart tissue of mice under diabetes, and Sirt3, which is mainly located in mitochondria, was down-regulated." (PMID 37958991, 2023). "Resveratrol, a GPER agonist, has been shown to counteract the effects of diabetes by increasing the activity and expression of Sirt1 and Sirt3 in the heart and improving cardiac mitochondrial function." (PMID 38134189, 2023). "Overexpression of Sirt3 attenuated anesthesia-induced learning and memory dysfunction and ameliorated diabetes-induced cognitive impairment and mitochondrial dysfunction." (PMID 38011257, 2023). "In individuals with diabetes, SIRT3 upregulates mitochondrial autophagy in the heart solely by inhibiting macrophage stimulating 1 (Mst1), and inhibiting SIRT3 expression impairs mitochondrial autophagy in myocardial cells, thereby exacerbating type 1 DCM." (PMID 37754811, 2023). "In conclusion, we demonstrated that CD38 deficiency protected mice from diabetes-induced diabetic cardiomyopathy by reducing pyroptosis and apoptosis via activating NAD+/Sirt3/FOXO3a signaling pathways." (PMID 37958991, 2023). "Morphological analysis of the CA1 pyramidal neuron dendrites in the hippocampal slices demonstrated that diabetes reduced spine number, which was reversed by SIRT3 overexpression." (PMID 37481555, 2023). "SIRT3 can also exert beneficial actions in diseases including diabetes and cardiovascular diseases which often coexist with AD." (PMID 36675125, 2023). "In our study, we found that the expression levels of Sirt3 and FOXO3a were significantly increased in the hearts of CD38-deficient mice or cardiomyocytes under the condition of diabetes." (PMID 37958991, 2023).